KRTAP4-4 (keratin associated protein 4-4)
Description:
In the hair cortex, hair keratin intermediate filaments are embedded in an interfilamentous matrix, consisting of hair keratin-associated proteins (KRTAP), which are essential for the formation of a rigid and resistant hair shaft through their extensive disulfide bond cross-linking with abundant cysteine residues of hair keratins. The matrix proteins include the high-sulfur and high-glycine-tyrosine keratins.
Synonyms: KAP4.13; KAP4.4; KRTAP4-13; KRTAP4.13; KRTAP4.4
Tractability: No criterion of Open Targets' tractability assessment is met for any kind of drug.
Gene: Protein-coding gene on chromosome 17 (41,159,649 to 41,160,748, reverse strand). Ensembl gene ENSG00000171396.
Pathways (Reactome):
Developmental Biology: Keratinization
Gene Ontology:
Molecular function: protein binding
Biological process: hair cycle
Cellular component: cytosol; keratin filament
Genetic constraint (gnomAD): Loss-of-function variants: 2 observed, 0.6 expected, observed/expected ratio (o/e) 3.31. That is too few expected variants to judge how well the gene tolerates losing a copy. Missense variants: 186 observed, 208.24 expected, observed/expected ratio (o/e) 0.89, 90% interval 0.79 to 1.01. Synonymous variants: 88 observed, 77.19 expected, observed/expected ratio (o/e) 1.14, 90% interval 0.96 to 1.36.
Homologues: Orthologues: mouse Krtap5-24 (47% identical), mouse Krtap5-26 (44% identical), mouse Krtap5-2 (41% identical), rat Krtap5-8 (40% identical), rat AABR07006049.1 (40% identical), mouse Krtap5-20 (37% identical). Paralogues in human: KRTAP4-12 (77% identical), KRTAP4-11 (75% identical), KRTAP4-9 (74% identical), KRTAP4-6 (73% identical), KRTAP4-8 (73% identical), KRTAP4-5 (69% identical), KRTAP4-3 (66% identical), KRTAP4-2 (63% identical), KRTAP4-7 (62% identical), KRTAP4-1 (52% identical), KRTAP9-1 (49% identical), KRTAP4-16 (49% identical), and 35 more.